GPX4 (glutathione peroxidase 4)
Diseases named in the same sentence as GPX4 in open-access papers (continued):
Sharing a sentence is not in itself a finding about the gene and the disease.
cancer (continued). "Here, the authors report that these cancers have a common vulnerability to GPX4 inhibition-induced ferroptosis and using CRISPR screen and lipodomic profiling, they identify HIF-2α- HILPDA axis promotes ferroptosis via enrichment of PUFA lipids." (PMID 30962421, 2019). "The expression levels of GPX4 in both the cancer cell lines treated with erastin were significantly lower than those in untreated cells." (PMID 31800616, 2019). "Increase in GPX4 levels promotes cell survival and resistance to ferroptosis in drug-tolerant cancer cells." (PMID 31288436, 2019). "It has been demonstrated that high therapy-resistant mesenchymal cancer cells strictly rely on the selenium-dependent GPX4 for survival." (PMID 29868472, 2018). "Accordingly, inactivation of GPX4 through GSH depletion with erastin, or with a direct GPX4 inhibitor, ultimately results in lipid peroxidation in cancer cells." (PMID 29868472, 2018). "Complementary to our previous study, we now assessed the effects of GPx4 overexpression in HCC and analysed correlations between GPx4 and cancer patient survival." (PMID 29515790, 2018). "In this study, changes in gene expression were observed for SELENOP, SELENOS, and TXNRD3 for all sample groups, while GPX4 was significant in the Irish cancers only and GPX1, SELENOH, and SELENON were differently regulated in the Czech CRCs." (PMID 30469315, 2018). "Some small molecules (e.g., erastin and RSL3) and clinical cancer drugs (e.g., sorafenib, sulfasalazine, and artesunate) induced cell death via the inhibition of system Xc− and GPx4 in various types of cancer cells." (PMID 30583467, 2018). "The lethal metabolic imbalance resulted from GSH depletion or inactivation of glutathione peroxidase 4 is the executor of ferroptosis within the cancer cell." (PMID 29375387, 2017). "It has been shown previously that increased GPX4 degradation contributes to ferroptotic cancer cell death." (PMID 28551825, 2017). "Recently, a distinctive iron‐dependent cell death, called ferroptosis has been primarily characterized in cancer cells and GPx4 is considered to be a central regulator of ferroptosis that is mediated by lipid peroxidation." (PMID 28203523, 2016). "Targeting SLC7A11 or GPX4 can sensitize radioresistant cancer cells to ferroptosis." (PMID 41596341, 2026). "This synergistic effect may be mediated by increased production of reactive oxygen species (ROS) and a weakening of the cancer cells' antioxidant defenses, including reductions in glutathione, GPX4, and catalase." (PMID 41972356, 2026). "Consequently, cancer cells can be rendered sensitive to ferroptosis through targeted agents or autophagy‐mediated GPX4 degradation." (PMID 41323827, 2025). "Moreover, FSP1, a ferroptosis suppressor acting independently of GPX4, has been implicated in NPC, and preclinical inhibitors such as iFSP1 have been shown to suppress the FSP1–CoQ10 axis and sensitize cancer cells to ferroptosis-inducing therapies." (PMID 41373599, 2025). "In addition, GSH depletion induces apoptosis in cancer cells in ferroptosis and leads to the inactivation of glutathione peroxidase 4 (GPX4)." (PMID 40486836, 2025). "GPX4 is a critical regulator of ferroptotic cell death; inhibiting GPX4 activity has been shown to sensitize cancer cells to ferroptosis and may help overcome resistance to conventional therapies." (PMID 40623982, 2025). "In 27 out of 33 cancer types, GPX4 expression differed significantly." (PMID 41142608, 2025). "Upregulated Gpx4 inhibits ferroptosis in cancer cells to acquire cisplatin resistance." (PMID 40843357, 2025). "This degrader causes ferroptosis in cancer cells, but it does not degrade GPX4 in immune cells, allowing the body to maintain its immune response to tumors." (PMID 40969276, 2025). "Therefore, targeting the regulation of GPX4, especially post‐translational regulation, has emerged as a new strategy to induce ferroptosis in cancer cells." (PMID 40070026, 2025).
cancer (continued). "Furthermore, we examined the expression of several key ferroptosis-related proteins in radioresistant cancer cells, including GPX4, SLC7A11, Nrf2, TfR1, and ACSL3." (PMID 40102409, 2025). "This study highlights the important role that sterols may play in the sensitivity of cancer cells to ferroptosis and may represent a potential means of sensitising MM cells to ferroptosis induced by GPX4 inhibition." (PMID 40853521, 2025). "A recent study showed that GPX4 inhibitors could enhance the response of cancer patients to immunotherapy by promoting T cell infiltration." (PMID 40746894, 2025). "Thus, XCT and GPX4 present promising molecular targets for ferroptosis inducers, aimed at disabling the intrinsic ferroptosis defense system to develop novel anti-cancer drugs." (PMID 40010136, 2025). "When GPX4 activity is inhibited, as in some cancer cells, it triggers ferroptosis." (PMID 40143112, 2025). "In addition, a variety of novel compounds have been designed and synthesized around the GPX4 target, such as ferrocene plus GPX4 inhibitors, which induce ferroptosis by modulating GPX4 activity, providing new strategies for cancer treatment." (PMID 40143112, 2025). "The GPX4 gene may serve as an accurate predictor of survival outcomes across a wide range of cancers." (PMID 41142608, 2025). "Notably, GPX4-targeting nanobodies were shown to induce ferroptosis in cancer cells, further demonstrating the therapeutic relevance of modulating ferroptosis in different disease contexts." (PMID 40276370, 2025). "Therefore, modulating key proteins such as GPX4 to regulate ferroptosis represents a promising strategy for cancer therapy." (PMID 41242017, 2025). "GPX4’s modulation of ferroptosis offers new avenues for cancer treatment." (PMID 40969276, 2025). "GPX4 is a selenoprotein that reduces lipid hydroperoxides and prevents ferroptosis in conditions of oxidative stress (ROS) with enhanced lipid peroxidation, to the advantage of surviving cancer cells." (PMID 40568132, 2025). "We treated control and OTUD5‐KO cells with nutlin‐3a and observed that knockout of OTUD5, in combination with nutlin‐3a treatment, led to a reduction in protein levels of OTUD5 and GPX4, thereby triggering ferroptosis in cancer cells and consequently inhibiting cell proliferation." (PMID 40070026, 2025). "Additionally, understanding the complex molecular interactions within the PTK2B/STAT3/GPX4 pathway is crucial for optimizing ferroptosis-based cancer therapies." (PMID 41166024, 2025). "Combining GLS1 or GPX1 inhibitors with a GPX4 inhibitor synergistically suppresses cancer growth." (PMID 40259435, 2025). "Although mounting evidence suggests that GPX4 significantly contributes to the development of certain cancers, its exact role in cancer biology remains to be fully elucidated, and a comprehensive pan-cancer analysis which leverages multi-omics integration, has not yet been performed." (PMID 41142608, 2025). "Consequently, we investigated the methylation levels of GPX4 across TCGA pan-cancers utilizing the UALCAN database." (PMID 41142608, 2025). "Notably, FSP1 has emerged as a novel ferroptosis inhibitor, and its specific inhibitor iFSP1 sensitizes certain cancer cell lines to GPX4 suppression." (PMID 41326356, 2025). "Also, silencing LDHB did not decrease SLC7A11 expression in KRAS wild-type cancer cells; in fact, an increase in SLC7A11 was observed in HT1080 cells after LDHB silencing, but LDHB silencing still sensitized KRAS wild-type cancer cells to GPX4 inhibition." (PMID 40090955, 2025). "In view of the pathological and clinical feature of GPX4 across different cancer types, we investigated whether GPX4 could be used as a potential biomarker for the diagnosis of human cancers." (PMID 41142608, 2025). "Evasion of cancer cell ferroptosis via GPX4 upregulation has been observed during GAC progression." (PMID 39905493, 2025).
cancer (continued). "Moreover, numerous treatments, including small-molecule inhibitors, natural products, and gene deletions, have been identified to suppress cancer progression by targeting GPX4 in CRC." (PMID 40746894, 2025). "The function of GPX4 in tumors is not yet fully understood, and further in-depth research into its regulatory mechanisms and clinical significance will be instrumental in devising novel therapeutic strategies for the prevention and treatment of human cancers." (PMID 41142608, 2025). "Based on these findings, GPX4 might play a crucial role in the biological processes of cancer progression." (PMID 41142608, 2025). "The therapeutic potential of GPX4 in cancer was investigated using publicly available datasets." (PMID 41142608, 2025). "Both GPX4 and system xc− are pharmacological targets of synthetic ferroptosis-inducing agents, with RSL3 and erastin having been major hits in screens for compounds toxic to otherwise highly treatment resistant RAS-mutated cancer cells." (PMID 40301648, 2025). "Moreover, recent CRISPR genetic screens and cancer literature revealed that cells with compromised MCI are particularly susceptible to loss of GPX4, the key phospholipid hydroperoxidase that guards against death caused by lipid peroxidation." (PMID 40770507, 2025). "Hence, targeting GPx4 to induce ferroptosis in cancer cells presents a promising strategy for anticancer drug development." (PMID 39908861, 2025). "This process is induced by GPX4 reduction, and the down-regulation of GPX4 leads to LPO formation in cancer cells, suggesting that ferroptosis may be a critical pathway in IR808-ATIPA + x-ray combined therapy." (PMID 40831788, 2025). "GPX4 is a crucial regulator in cancer cell research and ferroptosis." (PMID 40822852, 2025). "Interestingly, recent studies suggest that cisplatin can also enhance ferroptosis by inducing GSH depletion and inhibiting GPX4, providing a novel mechanism for cancer therapy." (PMID 40630134, 2025). "Since GPX4 is highly expressed in various cancer tissues, we hypothesize that it plays an oncogenic role in these tumors." (PMID 41142608, 2025). "GPX4 suppression is a crucial strategy for addressing cancer's resistance to chemotherapy." (PMID 40916076, 2025). "Importantly, cancer cells with diminished GPX4 expression or high oxidative stress are particularly dependent on DHODH activity, making them selectively sensitive to its inhibition." (PMID 41369379, 2025). "Rather than inhibiting antioxidant enzymes directly, enhancing SeP may reduce hepatic selenium retention and thereby limit the synthesis of selenoproteins such as GPx1 and GPx4, which support cancer cell survival under oxidative stress." (PMID 40818321, 2025). "Therefore, future research should focus on identifying cancers that are more responsive to GPX4 inhibitors and enhancing the efficacy of these inhibitors." (PMID 40969276, 2025). "Interestingly, in cancer cells, curcumin not only regulates iron levels but also disrupts antioxidant pathways such as GPX4/GSH, thereby promoting ferroptosis, suggesting a tissue- and dose-dependent action." (PMID 39935430, 2025). "Furthermore, it examines the molecular mechanism by which the autophagy receptors TAX1BP1 and SQSTM1 induce GPX4 degradation and impair cancer cell resistance to ferroptosis during copper‐ and erastin‐mediated autophagy processes." (PMID 41323827, 2025). "Therefore, the aim of this study was to investigate the expression patterns, prognostic significance, methylation status of GPX4, and the potential role of GPX4 in immune therapy across 33 different types of cancer." (PMID 41142608, 2025). "The stabilization of GPX4 promoted cancer cell survival under sorafenib‐induced oxidative stress." (PMID 41287824, 2025). "Furthermore, N6F11 was identified as a selective ferroptosis inducer that specifically degrades GPX4 via TRIM25-mediated ubiquitination in cancer cells because of its preferential expression." (PMID 40607253, 2025).
cancer (continued). "Gaining insight into GPX4’s mechanisms and biological roles could offer valuable therapeutic insights for cancer treatment." (PMID 41142608, 2025). "However, the Nrf2/HO-1/GPX4 axis was found to be crucial for reducing ROS levels and preventing ferroptosis in cancer cells and is an important target for chemotherapy drugs." (PMID 40242036, 2025). "Furthermore, PRDM1 and IRF, which exhibit higher activity in CD8+ T cells, induce ferroptosis in cancer cells by inhibiting the transcription of GPX4 and driving the expression of transferrin receptor, respectively, thereby improving the TME." (PMID 40454580, 2025). "First, we have detected the expression of GPX4 in pan-cancer tissues using an online database." (PMID 40746894, 2025). "However, as the cancer progresses, cells adapt by modulating iron metabolism and antioxidant defenses, such as upregulating GPX4 and SLC7A11, to suppress ferroptosis and enhance survival." (PMID 40066170, 2025). "GPX4 expression was correlated with various functional states across cancers." (PMID 41142608, 2025). "In another study, LRP8 was identified as a resistance factor in cancer cells, and its depletion was accordingly found to strongly reduce GPX translation by causing early ribosomal stalling and subsequent proteasome-mediated proteolysis of nascent GPX4." (PMID 40227202, 2025). "Inhibition of GPX4 has been shown to induce cancer cell death." (PMID 40191227, 2025). "Next, we evaluated the role of GPX4 mRNA expression in predicting pan-cancer prognosis." (PMID 40746894, 2025). "Furthermore, organoids derived from intestinal stem cells have underscored the significance of IFNγ as a pivotal cytokine that can halt cancer stemness and initiate GPX4-dependent ferroptosis." (PMID 40427552, 2025). "Cancers reliant on cystine-glutamate transporters or GPX4 may benefit from targeting these pathways." (PMID 39055871, 2024). "Indeed, overcoming their pharmacokinetics and selectivity issues remains a challenge in the development of new GPX4 inhibitors for cancer therapy." (PMID 38539554, 2024). "Furthermore, inhibiting GPX4 can sensitise cancer cells to ferroptosis and effectively restrain the development of human cancers." (PMID 38070189, 2024). "However, some cancer cell lines are still resistant to ferroptosis upon GPX4 inactivation, indicating the existence of alternative mechanisms." (PMID 39769097, 2024). "GPX4 is an important regulator of ferroptosis in cancer cells." (PMID 38200039, 2024). "In addition, the disulfide cross-linked polymerization coat was degraded, and the released SRF down-regulated GPX4 expression in cancer cells, further promoting ferroptosis." (PMID 39276361, 2024). "However, inhibiting GPX4 has been ineffective in inducing ferroptosis in several cancer cell lines, suggesting the existence of an alternative resistance mechanism." (PMID 38206305, 2024). "Notably, GPX4 deficiency is embryonically lethal in mice, making the targeting of FSP1 a potentially safer choice in cancer treatment." (PMID 38414669, 2024). "GPX4's high expression can lead to a good prognosis in DLBCL patients, which may be related to its inhibition of cancer cell proliferation, high expression of key pathogenic genes, and infiltration of immune B cells." (PMID 38333875, 2024). "The promotor of the gene driving expression of the Gpx4 gene for example is less methylated in cancer cells contributing to higher levels of the protein in these cells, whereas elevated methylation of GpG islands of Gpx4 and FSP1 leads to diminished protein levels." (PMID 38908072, 2024). "Interestingly, this pathway is upregulated in various ferroptosis-resistant cancer cell lines similar to GPX4 upregulation." (PMID 39188677, 2024).
cancer (continued). "Therefore, inhibition of IPP can sensitize cancer cells to ferroptosis in a GPX4/FSP1-dependent manner." (PMID 38459004, 2024). "GPX4 plays a vital role in the inhibition of ferroptosis in several cancer types." (PMID 38738178, 2024). "One study showed that persister cells of different cancers (breast, melanoma, lung, and ovarian cancers) were vulnerable to GPX4 inhibition, which led to the accumulation of lipid hydroperoxides and ferroptosis upon the withdrawal of ferrostatin-1, a ferroptosis-rescuing antioxidant." (PMID 39061847, 2024). "GPX4 protein degraders can also serve as ferroptosis inducers for cancer treatment." (PMID 39624080, 2024). "Furthermore, the combined inhibition of GPX4 and mitochondrial dihydroorotate dehydrogenase (DHODH) effectively eradicated GPX4high cancer cells, highlighting the synergistic induction of ferroptosis resistance by GPX4 and DHODH." (PMID 39061847, 2024). "H. pylori infection upregulates GPX4 expression and activity through TCF4, leading to a high antioxidant state of cancer cells and inhibition of iron-induced death; thus, GPX4 may be a potential target to enhance chemosensitivity in patients with advanced GC." (PMID 38952556, 2024). "Strategies aimed at blocking PROM2 expression or function may enhance cancer cell sensitivity to ferroptosis induced by GPX4 inhibitors." (PMID 39624080, 2024). "The increased mitochondrial ROS in RSL3 treated group demonstrated that low concentration RSL3 had a potential effect on mitochondrial GPX4 activity and inhibited the enzyme catalyzing hyperoxide, which made cancer cells vulnerable to subsequent oxidative stress." (PMID 38347507, 2024). "However, accurately targeting cancer cells requires real-time monitoring of GPX4 and organelle-specific GSH levels in living cells." (PMID 38844964, 2024). "Thus, chemoresistance and cancer cell survival under high ROS burden obligates high GPx4 and SR‐B1 expression through SREBF2." (PMID 38263873, 2024). "According to this result, GPX4 is upregulated in cancer tissue compared to normal DLBCL tissue." (PMID 38333875, 2024). "Additionally, it synergizes with ferroptosis inducers to amplify these effects in cancer cells with high expression of GPX4 (GPX4high)." (PMID 38534454, 2024). "Small molecules targeting GPX4 are emerging as effective inducers of ferroptosis in cancer therapy." (PMID 39239068, 2024). "Furthermore, glutamine deprivation results in the decreased expression of GPX4, implying that targeting glutaminolysis influences the chemoresistance of cancer cells." (PMID 39519171, 2024). "The current ferroptosis-inducing strategies used to eliminate therapy-resistant cancer cells usually target GPX4 by downregulating its expression or by inhibiting its activity via the reduction of its cofactor, GSH, thus disturbing the balance between prooxidant and antioxidant systems." (PMID 38879508, 2024). "Therefore, regulation of GPX4 levels inside cells induces cancer cell ferroptosis, thereby blocking further spread and metastasis." (PMID 38469234, 2024). "Their results suggested that the ferroptosis sensibility can be predicted by the NAD(P)H and CoQ levels and that combining GPx4 inhibitors with FSP1 inhibitors might be a better cocktail for ferroptosis induction in therapy-resistant cancer cells." (PMID 39201524, 2024). "However, GSH depletion has been effective in inhibiting PDAC cell proliferation, and rapamycin has shown anti-cancer activity through GPx4 degradation." (PMID 39594547, 2024). "Furthermore, ORes regulates the EGFR/PI3K/AKT/GPX4 axis, targeting both ferroptosis and key cancer-related pathways, which distinguishes it from other ferroptosis inducers." (PMID 39881871, 2024). "Furthermore, ACSL4/GPX4/PHLDA2 triple-knockout cancer cell lines were resistant to ferroptosis, indicating that the mechanism is independent of GPX4." (PMID 39188677, 2024).